IL2 (interleukin 2)
Diseases named in the same sentence as IL2 in open-access papers (continued):
Sharing a sentence is not in itself a finding about the gene and the disease.
tumor (continued). "This phenotypic shift in both the spleen and TME indicates effective tumor targeting by cytotoxic CD8+ T cells, potentially supported by IL-2 secretion from CD4+ T cells in both compartments." (PMID 40343532, 2025). "Although cytokines such as IL-2 and TNF-α are also indicative of immune activation, IFN-γ was selected as the primary marker due to its direct relevance to anti-tumor activity." (PMID 40643554, 2025). "Functional assessments demonstrated that while both the DAP12-containing CAR and its predecessors exhibited comparable tumor-killing, the DAP12 construct produced lower levels of IFNγ, TNFα, and IL-2, during tumor cell lysis." (PMID 40948803, 2025). "Subsequently, coculture with EDEM3OE CRC cells significantly inhibited T‐cell‐mediated tumour killing as indicated by an increased percentage of viable cells and attenuated IFN‐γ and IL‐2 secretion in the corresponding samples." (PMID 39754316, 2025). "Activated CD4+ T cells have a range of roles; they can directly activate CD8+ CTLs through interleukin-2 (IL-2) secretion, CD40 signalling to B cells, and mediating direct anti-tumour activity." (PMID 41445691, 2025). "Activated NF-κB, ERK, and AKT can mediate the release of IL-2 and IFN-γ from T cells, and these cytokines can in turn promote T cell proliferation and enhance tumor cell killing." (PMID 40276607, 2025). "Responses to cytokines promoting T cell function (IL-1-β, IL-2, IL-7, IL-15, IFN-α1, IFN-β, IFN-ω, IFN-γ) were downregulated in T cell aggregates relative to the tumor core, macrophage and DC islands but upregulated compared to other niches." (PMID 41510257, 2025). "HIF-1α can promote the IL-2 and IL-12 cytokine-stimulated OXPHOS response, and promote the killing effect of NK cells on the tumor tissues." (PMID 40696413, 2025). "The expression of T cell activation receptor IL2R, along with various anti-tumor secretory factors (GZMB, IFNγ) and the inflammatory cytokine IL2, showed strong correlation with intracellular NAD+ levels." (PMID 40846839, 2025). "designed immune agonist-anchoring liposomes to co-deliver IL-2 and an anti-CD137 antibody, which promoted tumor infiltration of CD8+ T cells, enhanced cytokine and granzyme secretion, and elicited strong antitumor responses while reducing systemic toxicity." (PMID 41181109, 2025). "OX40L potentiates CD8+ cytotoxic T lymphocyte effector functions by inducing IL-2 and IFN-γ secretion, which augments tumor-antigen recognition and clonal burst size." (PMID 41561762, 2025). "Secretion of IL-2, IFN-γ, and TNF-α by these cells directly suppresses tumor growth while simultaneously enhancing the cytotoxic activities of other immune components." (PMID 41320679, 2025). "Lingzhi polysaccharides (50–200 μg/mL) stimulated T lymphocytes to release IL-2 and IFN-γ, thereby enhancing T cell activation and cytotoxicity against tumor cells." (PMID 40733125, 2025). "Pro-tumor cytokines like IL-10 and TGF-β promote an immune-evasive environment, while antitumor cytokines like IL-2 and TNF-α strive to elicit immune-mediated tumor destruction." (PMID 40309351, 2025). "In the TME, interferon-γ (IFN-γ), interleukin-2 (IL-2), and tumor necrosis factor-α (TNF-α) play roles in anti-tumor immunity." (PMID 40183013, 2025). "Specifically, positive selection resulted in a significantly increased in vitro secretion of IL-2 and IFN-γ but a decreased in vitro tumor killing rate." (PMID 40148988, 2025). "RT-qPCR analyses of tumor tissues and splenic CD4+ T cells revealed an upward trend in IL-2 expression, prompting further investigation into IL-2 expression within the lymphatic system." (PMID 40343532, 2025). "The water extract of T. angustifolia inhibits the growth of Lewis lung cancer tumors in mice, increases serum levels of IL-2 and TNF-α, arrests tumor cells in the G1 phase, and induces tumor cell apoptosis." (PMID 40290444, 2025).
tumor (continued). "Cytokines secreted by type 1 helper T cells (Th1), such as interleukin (IL)-2, IL-12, IL-18, interferon γ (IFN-γ), and tumor necrosis factor (TNF), participate in anti-tumor defense." (PMID 41561739, 2025). "ELISA results demonstrated a significant increase in the levels of anti‐tumor cytokines IFN‐γ, TNF‐α, and IL‐2 following treatment with 10e." (PMID 39680480, 2025). "TUBA1B expression also positively correlated with immune-related pathways like interferon-alpha/gamma response, IL-2/STAT5 signaling, and IL6/JAK/STAT3 signaling, indicating TUBA1B’s significant role in the tumor immune microenvironment (TIME)." (PMID 39968182, 2025). "Treatment of tumors resected from tumor-implanted hu-BLT mice infused with sNK and treated with IL-2 substantially increased the levels of MHC class I expression when compared to mice implanted with tumors alone." (PMID 40805135, 2025). "Among these, IL-1β, IL2, IL6 play critical roles in activating immune cells and amplifying proinflammation responses, while TNFα and IL27 can directly inhibit the growth of tumor cells." (PMID 40046011, 2025). "They enhance anti-tumor immunity by secreting IFN-γ, IL-2, IL-4 and IL-17, which activate cytotoxic T lymphocytes (CTLs), natural killer (NK) cells, and macrophages." (PMID 40438115, 2025). "In contrast, Th1 cytokines, including IL-2 and IFN-γ, favor activation of cytotoxic T lymphocytes and NK cells, supporting an anti-tumor immune response." (PMID 40807278, 2025). "The release of pro-inflammatory chemokines and cytokines, such as IL-1, IL-2, IL-6, CCL-2, CCL-8, TNF-α and TGF-β, facilitate the recruitment of brain-resident immune cells to the tumour site." (PMID 41301734, 2025). "The results demonstrated significantly higher mRNA expression of IFN-γ, TNF-α, IL-2, IL-12a, CXCL9, and CXCL10 in the tumor tissue of the PD-L1-KO/ZG16 overexpression group compared to the control group." (PMID 39958358, 2025). "Though often co-administered with IL-2, its efficacy is undermined by the TME, particularly transforming growth factor-beta (TGF-β), programmed death-ligand 1 (PD-L1) expression, and poor tumor-homing ability." (PMID 40904467, 2025). "Tumor Tumor-infiltrating T lymphocytes, key effector cells of the immune system, can secrete anti-tumor cytokines (IFN-γ and IL-2)." (PMID 40977688, 2025). "PEGylated liposomes functionalized with interleukin-2 (IL-2) and anti-CD137, immunostimulatory agents that activate CTLs and NK cells, accumulated quickly towards the tumor, improved immune cell infiltration, and stimulated cytokine production." (PMID 40872479, 2025). "Additionally, Hallmark pathways such as IL2 STAT5 signaling and allograft rejection were upregulated, reflecting the heightened immune activation in tumors which could foster a hostile environment for tumor growth." (PMID 40094000, 2025). "The DNA aptamer specific to PD-L1, aptPD-L1, stimulated IFN-γ, IL-2, C-X-C motif chemokines, TNF-α, proliferation of cytotoxic and helper T cells infiltrated in tumours and also inhibited in vivo tumour growth." (PMID 41012445, 2025). "Elevated levels of IL-2 and IFN-γ, and decreased IL-10 were observed in OSCC patients, correlating with tumor differentiation and stage." (PMID 40958269, 2025). "IL‐2 and Y45 treatments showed a mild to substantial increase in CD8+ T cell infiltration compared to D20, with T cells largely confined to the tumor periphery." (PMID 40108893, 2025). "CIK cell therapy is an adoptive immunotherapy approach where T cells are expanded with cytokines, such as IL-2 and IFN-γ, to generate highly cytotoxic lymphocytes capable of targeting and killing tumor cells." (PMID 40356763, 2025). "The proportion of CD45+ immune cells was higher in sNK-infused tumor-implanted BLT mice as compared to mice implanted with tumors alone, and the addition of IL-2 further increased the levels of CD45+ immune cells within the tumor cultures." (PMID 40805135, 2025).
tumor (continued). "For example, IL-2-modified sEVs loaded with miRNAs directed against Bcl-2 and VEGF were able to improve immune responses and tumor suppression." (PMID 40688030, 2025). "Moreover, IL-2 secretion may support the enhancement of tumor immune responses." (PMID 40343532, 2025). "Using the OMIQ platform and CyTOF, they characterized tumor immune infiltration and found that MC38 and YUMMER2.1 cells with B2M KO responded to anti-PD-1 treatment alone or in combination with IL-2 agonists, mediated by CD4+ T cells and NK cells." (PMID 40191187, 2025). "Our findings demonstrate a significant increase in cytokines such as IL-2, IL-18, GM-CSF, IFN-γ, and MCP-1 following tumor removal." (PMID 40711287, 2025). "This nanoparticle enhances tumor immunotherapy by disrupting mitochondrial function and activating CD4+ and CD8+ T cells, thereby increasing IL-2 and TNF-α expression, and significantly inhibiting tumor growth." (PMID 39742149, 2025). "We found that CRTC1 overexpression in tumor cells upregulates PD-L1, suppresses IFN-γ and IL-2 production, reduces CXCL10/11 secretion, and impairs T-cell cytotoxicity." (PMID 40977688, 2025). "VNP, VNPCon-IL2 and VNPSORT-IL2 were injected 10 days post-tumor inoculation in a 4T1 syngeneic mouse model." (PMID 41041051, 2025). "In fact, tumor-infiltrating Tregs are frequently subjected to chronic TCR stimulation and reduced IL-2 availability—conditions that favor the upregulation of pro-apoptotic molecules such as BIM, rendering these cells susceptible to apoptosis." (PMID 40909289, 2025). "Increased tumor-infiltrating lymphocytes (TILs) and circulating IFN-γ and IL-2, as well as increased T cell memory populations, were found post-vaccination in survivors." (PMID 41374974, 2025). "The T cells released cytotoxic substances such as perforin and granzyme, and activated other immune cells by secreting interleukin (IL)-2 and IFN-γ, thus augmenting the anti-tumor immune response." (PMID 41030448, 2025). "These CD8+ T cells release IL-2, which promotes the expression of the anti-apoptotic protein ICOS on tumor-Tregs, facilitating their accumulation." (PMID 40636453, 2025). "Pre-clinical data show that PD-1 blockade (nivolumab) enhanced CAR-iNKT proliferation, cytokine production (IL-2, TNF-α, IFN-γ, and granzyme B) and effectively reversed CAR-iNKT exhaustion upon tumor rechallenge, translating into deeper tumor control." (PMID 40718496, 2025). "CD4+ helper T cells augment this response by producing interleukin-2, tumor necrosis factor-α, and interferon-γ, which promote CTL function, enhance macrophage and NK cell activity, and increase tumor antigen presentation." (PMID 41194932, 2025). "For example, IL-2 modified sEVs containing miRNAs against Bcl-2 and VEGF stimulated immune responses, tumor suppression and anticancer actions." (PMID 40688030, 2025). "These TILs were associated with the generation of pro-inflammatory cytokines, such as interleukin-2 (IL-2), tumor necrosis factor-α (TNF-α), and interferon-gamma (IFN-γ), suggesting metformin’s effect for activating anti-tumor immune responses." (PMID 40005128, 2025). "Characterization of T cell subsets revealed that almost all tumor spheroid-activated T cells were CD8+, while IL-2-activated T cells were CD4+." (PMID 40123996, 2025). "Compared to VNPCon-IL2, VNPSORT-IL2 + US group exhibited lower IL-2 levels in serum and non-tumor tissues." (PMID 41041051, 2025). "Strong associations with grade ≥ 3 CRS were further observed with peak CAR T cell levels normalized to tumor burden (SPD), IL-6 peak, IL-2 AUC, and IL-1RA AUC." (PMID 40536814, 2025). "Exhausted T cells show increased expression of inhibitory receptors, including CTLA-4 and PD-1, and reduced production of effector cytokines, such as IL-2, tumor necrosis factor (TNF-α), and IFN-γ, further weakening the immune response against the tumor." (PMID 40006624, 2025).
tumor (continued). "On the one hand, TGF-β can inhibit tumor cell growth, IFN-γ and IL-2/12/15 suppress cell proliferation by enhancing the cytotoxicity of lymphocytes or bone marrow cells." (PMID 41333471, 2025). "TILT-123 (igrelimogene litadenorepvec) is an engineered OVs that selectively replicates in cancer cells and expresses dual transgenes IL-2 and TNF-α, designed to enhance tumor immune infiltration and cytotoxic T-cell responses." (PMID 41024300, 2025). "Further confirmation of T cell dysfunction in the setting of HIV included decreased cytokine production (IL-2 and IFN-γ) in response to exposure to tumor cells." (PMID 40459946, 2025). "Conversely, B7-H3 upregulation was observed to promote the secretion of IL-2, IL-6, IL-17, and TGF-β1, while concurrently leading to reduced IFN-γ production in T-cells within the tumor microenvironment (TME)." (PMID 40214484, 2025). "CAFs, a key component of the TME, secrete a range of cytokines—including TGF‐β, ILs (IL‐2, IL‐6), chemokines (CXCL2, CXCL5, CXCL12), and FGF7—to support tumor cell proliferation." (PMID 41164803, 2025). "Upon reinfusion, CAR-T cells engage tumor surface antigens, triggering perforin/granzyme-mediated apoptosis and pro-inflammatory cytokine storms (e.g., IFN-γ, IL-2) that amplify bystander immune activation." (PMID 41181090, 2025). "Conversely, eliminating IL-2 expression using tacrolimus (FK506), an inhibitor of calcineurin, also diminished the difference in tumor growth, as well as the IFN production by WT and Gsdmd–/– lymphocytes, including CD4+ T, CD8+ T, and NK cells." (PMID 40759573, 2025). "Nevertheless, to date few human trials have evaluated IL-2-augmented CAR-T, and the balance of enhanced anti-tumor effect versus added immune toxicity remains to be fully characterized." (PMID 41584600, 2025). "In conjunction with replication, the virus produces interleukin-2 (IL-2) and tumor necrosis factor (TNF), which results in the recruitment of immune cells to the tumor microenvironment (TME)." (PMID 40107242, 2025). "To date, tumor-directed delivery of IL-15/4-1BBL (scFv anti-FAP), IL-2/TNF (scFv anti-EDA) and IL-2/IL-12 (scFv-Fc anti-CD30, LAIR2), has shown significant therapeutic effects in preclinical tumor mouse models." (PMID 40370435, 2025). "For instance, it was demonstrated in pre-clinical models that targeting IL-2 to CD8+ T cells promotes robust effector T cell responses and potent anti-tumor immunity." (PMID 41050699, 2025). "For example, abnormal blood vessels help tumors escape the attack of the immune system, Endostar normalizes abnormal tumor blood vessels, increases the infiltration of immune effector cells, and increases CD4+ or IL-2, which proves immunity." (PMID 39928822, 2025). "The secretion of exosomal peptide MHC I is transferred to CD8+ T cells under the influence of released IL-2 and exosomal CD80, leading to increased proliferation of CD8+ T cells and the production of a more robust anti-tumor immune response in vivo." (PMID 40141358, 2025). "Compared with paired surgical margins, tumour tissues exhibited an inflammatory shift characterised by increased IL-1β and IL-6 alongside reduced TNF-α, IFN-γ, IL-12 and IL-2." (PMID 41465261, 2025). "PGE2 plays a critical role in suppressing the response of CD8+ T Cells to interleukin-2 (IL-2) signaling, thereby preventing the expansion of stem-like CD8+ T Cells and tumor-infiltrating CD8+ T Cells." (PMID 40356601, 2025). "Simultaneously, IL-2 and IFN-γ secretion is reduced, which further reduces NK cell proliferation and activation and ultimately promotes tumor proliferation." (PMID 40027183, 2025). "Nanoparticles loaded with IL-2 enhance Th1-biased CD4+ responses, boosting IFN-γ and IL-2 secretion while improving cytotoxic activity against tumor cells." (PMID 40860882, 2025).
tumor (continued). "The heightened IL-2 levels in the TIME of PTC accompanied by HT can foster infiltration of CD8 + T cells, thereby boosting the anti-tumor effect." (PMID 40313970, 2025). "Importantly, when the reduced IL-2 levels were overridden by supplementation with murine recombinant IL-2, the difference in IFN production by WT and Gsdmd–/– CD8+ TILs was diminished, which was associated with the comparable tumor growth between the two groups." (PMID 40759573, 2025). "These approaches merge IL-2 with antibodies directed at TAAs (e.g., EpCAM, GD2, CD20, and CEA) or tumor extracellular matrix (ECM) components, enabling selective delivery to the TME and local immune activation." (PMID 40508202, 2025). "Among these, immunocytokines incorporating IL-2, IL-12, or TNF have demonstrated the most favorable tumor-homing properties and antitumor activity." (PMID 41568361, 2025). "These molecules augment IL-2 production and promote the development of long-lived effector and memory T cells, thus improving TIL persistence in hostile tumor environments." (PMID 40475782, 2025). "We examined cytokine secretion profiles (IL-2, IL-4, IL-6, and IFNG) from activated T cells (CD69, IL-2RA, CD38, and HLA-DRB1) to evaluate T-cell activation in the CM tumor microenvironment, revealing consistently low expression levels." (PMID 40959090, 2025). "CRTC1 knockdown potentiated the therapeutic efficacy of atezolizumab, evidenced by xenograft tumor regression, increased CXCL10/11 expression, and elevated serum concentrations of IFN-γ and IL-2." (PMID 40977688, 2025). "In our study, the model group showed decreased IL-2 and elevated IFN-γ levels, indicating reduced immune surveillance and a potential decline in the immune system’s ability to clear infections, tumor cells, and repair aged tissues." (PMID 40906203, 2025). "In tumor-bearing mice, Lingzhi extract (GLE; 200–400 mg/kg) was known to upregulate cytokines such as IFN-γ, IL-2, and TNF-α, thus producing T cell-mediated antitumor immunity." (PMID 40733125, 2025). "As a result, CD4+ T cells exhibited increased IL-2 production, CD8+ T cells secreted more IFN-γ, and overall tumor growth was significantly reduced." (PMID 40940834, 2025). "In LLC cells, CRTC1 upregulated tumor cell PD-L1 expression, suppressed T cell-derived IFN-γ and IL-2 production, diminished endogenous CXCL10/11 secretion, and impaired T cell proliferation and cytotoxicity." (PMID 40977688, 2025). "Lnc-Tim3 is upregulated in tumor-infiltrating CD8 T cells of HCC patients and is negatively correlated with the production of IFN-γ and IL-2." (PMID 40352941, 2025). "On the other hand, Treg cells consume IL-2 and release inhibitory cytokines such as TGF-β and IL-10, leading to T-cell apoptosis and promoting tumor growth." (PMID 40458394, 2025). "Specifically, administration of 2M3B1PP and IL-2 preceding Vδ2-enriched autologous PBMC adoptive cell therapy, with low-dose IL-2 and/or zoledronate as adjunct(s), facilitated prolongation of tumor doubling time." (PMID 40148988, 2025). "Pseudohypoxia induced by HIF-PH inhibitors activates antitumor immune responses, at least in part, through the induction of IL-2 secretion from CD4+ T cells in the spleen and tumor microenvironment, thereby enhancing immune efficacy against MSS CRC." (PMID 40343532, 2025). "Timed administration of CD25-biased IL-2 treatment after RT favored intratumoral expansion of CD8+ T cells over regulatory T cells, which resulted in comparable anti-tumor effects as with RT plus IL-2Rβ (CD122)-biased IL-2 immunotherapy." (PMID 40502703, 2025). "A recent investigation conducted a synergistic approach in oncology by combining an autologous tumor cell vaccine, ACT, with IL-2 in canines suffering from OS." (PMID 40149640, 2025). "Moreover, tumor sEVs may be able to specifically reduce lymphocytes’ responses to IL2." (PMID 40407494, 2025).